STK11 (serine/threonine kinase 11)
Diseases named in the same sentence as STK11 in open-access papers (continued):
Sharing a sentence is not in itself a finding about the gene and the disease.
lung adenocarcinoma (continued). "STK11 is recognized significant gene in cancer which induces tumor heterogeneity, promotes different responses to therapies and is among the most often mutated genes in lung adenocarcinoma." (PMID 35512017, 2022). "Interestingly, STK11 deletion seems to drive lineage transformation to squamous-cell carcinoma in KRAS mutated lung adenocarcinoma." (PMID 35251972, 2022). "Moreover, the analysis of patients’ survival with early stage lung adenocarcinoma in the TCGA PanCancer data set also highlighted poorer overall survival in patients with STK11 mutations." (PMID 33572782, 2021). "In animal studies of lung adenocarcinoma, it has been found that the inactivation or mutation of STK11 will be related to the change of the tumor microenvironment and the decrease of cytotoxic CD8+ cell infiltration, which will lead to the separation of the tumor from the body’s immune monitoring." (PMID 33633793, 2021). "In addition to lung adenocarcinoma, some pulmonary large-cell neuroendocrine carcinomas can also harbor STK11 mutations." (PMID 33572782, 2021). "LKB1 is encoded by the STK11 gene that is frequently altered in lung adenocarcinomas." (PMID 34203378, 2021). "Furthermore, it has been demonstrated that concomitant mutations in KRAS and STK11 confer poor survival in lung adenocarcinoma patients but their role in response to different kinds of treatments, including immunotherapy, need to be further elucidated." (PMID 32365882, 2020). "Genetic alterations of STK11 were also found to play a causal role in lung adenocarcinoma." (PMID 31845182, 2020). "Besides, Serine/Threonine kinase 11 (STK11) mutation is the main driving factor of primary resistance of PD-1 inhibitors in lung adenocarcinoma (LUAC) with KRAS mutations." (PMID 33344447, 2020). "Furthermore, STK11/LKB1 mutations in lung adenocarcinoma was correlated with primary resistance to anti-PD1 therapy." (PMID 32612833, 2020). "Moreover, co-mutation in KRAS and STK11/LKB1 contributed to a lower objective response rate in lung adenocarcinoma treated with nivolumab." (PMID 32793604, 2020). "Similarly, KRAS and STK11 mutations are less frequent in low TTP-expressing lung adenocarcinomas than in the high TTP-expressing cohort." (PMID 25541715, 2014). "Additionally, molecular profiling of lung adenocarcinoma has identified a high frequency of mutations in the tumor suppressors serine threonine kinase 11 (STK11–17%) and Kelch-like ECH associated protein 1 (KEAP1 - 17%), based on the analysis of 230 samples from the TCGA database." (PMID 39955067, 2025). "Ranks as the third most frequently mutated gene in lung adenocarcinoma and demonstrates a significant co-mutation propensity with KRAS mutations, collectively defining the distinct biological KL (KRAS/STK11 co-mutant subtype)." (PMID 41541668, 2026). "Concurrent KRAS + STK11 alterations were identified in 23.5% of cases, compared with The Cancer Genome Atlas (TCGA) cohorts of other lung adenocarcinomas (11/566, 2.0%) and HCC (0/372, 0%)." (PMID 42096087, 2026). "In lung adenocarcinoma, STK11 depletion results in increased expression of mesenchymal markers and enhanced cell viability." (PMID 41051525, 2025). "This inactivation of STING represents a novel immune evasion strategy, particularly in lung adenocarcinomas harboring co-mutations in KRAS and STK11, where it contributes to resistance against host immune responses." (PMID 40806276, 2025). "PER1 mRNA and protein are upregulated in STK11-mutant lung adenocarcinoma tumors and STK11-knockout human bronchial epithelial cells (HBEC3-KT)." (PMID 40715535, 2025). "In the Cancer Genome Atlas Lung Adenocarcinoma (TCGA LUAD) dataset, we found that, within KRAS-mutant tumors, those with STK11 mutations had higher PER1 mRNA expression (p = 0.0224) than those with wildtype LKB1." (PMID 40715535, 2025).
lung adenocarcinoma (continued). "For example, in STK11/LKB1-mutant lung adenocarcinoma, tumor cells export lactate via MCT4, which promotes M2-like polarization of TAMs while impairing T cell function." (PMID 41152975, 2025). "Co-mutations such as STK11/LKB1 and KEAP1 correlate with “immune-cold” phenotypes and poor responses to immune checkpoint inhibitors in lung adenocarcinoma." (PMID 41170373, 2025). "In 1817 KRAS-mutant lung adenocarcinomas, KEAP1 and SMARCA4 mutations correlated with metastasis and poor survival, while STK11’s impact varied by metastatic site and KEAP1 status." (PMID 40758706, 2025). "A549 STK11/KRAS co-mutant lung adenocarcinoma cells are more sensitive to GLUT1 knockdown than other LUAD lines, however, they continue to proliferate." (PMID 40069402, 2025). "It is important to mention here that STK11/LBK1 (Serine/threonine kinase 11, also known as liver kinase B1) is also frequently mutated in K-RAS mutant lung adenocarcinomas." (PMID 39682179, 2024). "MSLN showed a 4.37 and 2.61 absolute fold upregulation in STK11 and KEAP1 mutated lung adenocarcinoma (LUAD) patient population, respectively." (PMID 39186767, 2024). "Concurrent loss-of-function mutations in STK11 and KEAP1 in lung adenocarcinoma result in significantly elevated expression of ferroptosis-protective genes, such as AKR1C1/2/3, and resistance to pharmacologically induced ferroptosis." (PMID 38698462, 2024). "In contrast, LCNEC II exhibits alterations in NSCLC-type serine/threonine kinase 11 (STK11), Kelch-like ECH-associated protein 1 (KEAP1), and Kirsten rat sarcoma virus (KRAS); these are commonly seen in lung adenocarcinomas too." (PMID 38693435, 2024). "STK11 encodes the tumor suppressor liver kinase B1 (LKB1), which suppresses tumor growth, and its mutation occurs in approximately 30% of KRAS-mutant lung adenocarcinoma cases; this mutation can promote KRAS-driven cancer growth and early metastasis." (PMID 39037971, 2024). "In lung adenocarcinoma, KRAS mutations accompanied by Stk11/Lkb1 deletion were found to promote resistance to PD-1/PD-L1 inhibitors." (PMID 38782895, 2024). "Mutations in STK11 and KEAP1 are associated with resistance to ICI treatment in lung adenocarcinoma, but these mutations are difficult to sufficiently predict the efficacy of ICI treatment in SMARCA4-UT." (PMID 39497014, 2024). "Alternatively, STK11/LKB1 mutations, which frequently co-occurs with KRAS-mutations in lung adenocarcinomas, were associated with poor synergy between RT and anti-PD-1 in vivo." (PMID 37377970, 2023).
lung adenocarcinoma (continued). "STK11 and KEAP1 were considered to be associated with poor prognosis in patients diagnosed with lung adenocarcinoma." (PMID 37384291, 2023). "Among KRAS-mutant lung adenocarcinoma, a particularly aggressive subset with STK11 comutations had higher repstress scores compared with tumors without comutations." (PMID 36381660, 2022). "The comutation of STK11/LKB1 and the comutation of KEAP1/NFE2L2 were identified as genomic drivers for primary resistance to immune checkpoint inhibitors in KRAS-mutated lung adenocarcinoma." (PMID 36230855, 2022). "KRAS is the most common oncogenic driver in LUAC, and STK11 alterations have been shown to confer primary resistance to PD-1 axis blockade in KRAS mutant lung adenocarcinomas." (PMID 36273184, 2022). "It was reported that STK11/LKB1 alterations as a genomic driver of primary resistance to PD-1 axis inhibitors in KRAS mutant lung adenocarcinomas." (PMID 36248982, 2022). "In KRAS-mutant lung adenocarcinoma, the alterations of STK11/LKB1 exert effects in resisting the PD-1/PD-L1 inhibitors." (PMID 36034461, 2022). "A recent research implicated that the diversity of KRAS-mutant lung adenocarcinomas (LUADs) is associated with different characters, such as KRAS dependency, immunogenicity, and STK11/KEAP1 comutations." (PMID 35945957, 2022). "In two separate lung adenocarcinoma cohorts, patients with KRAS and STK11/LKB1 co-mutations showed lower ORR compared with KRAS mutation alone and one of the cohorts noted a significantly lower PFS and OS during immunotherapy treatment." (PMID 35222404, 2022). "STK11 and KEAP1 co-mutated lung adenocarcinoma, which are associated with aggressive tumor growth and immunotherapy resistance, had higher repstress scores compared with lung adenocarcinoma without concomitant loss of these genes." (PMID 36381660, 2022). "To further explore the value of BMP5 in clinical treatment, we first analyzed the correlation of mRNA expression between BMP5 and EGFR/STK11, which are critical molecular in targeted therapy and immunotherapy of lung adenocarcinoma." (PMID 34745928, 2021). "For instance, it has been found that STK11/LKB1 mutations act as the main driver of immune escape and intrinsic resistance to PD-1 blockade in KRAS-mutant lung adenocarcinoma (LUAD)." (PMID 35070998, 2021). "A clinical trial reported that STK11/LKB1 mutations, the most prevalent genomic driver of PD-1 blockade resistance, are negatively related to therapy in KRAS-mutant lung adenocarcinoma." (PMID 34930377, 2021). "Coexisting alterations in KEAP1 and STK11 among other genes define a subset of lung adenocarcinoma unresponsive to immunotherapy." (PMID 33889302, 2021). "Specifically, clinical studies have demonstrated that nonsense variants in STK11, which predict loss of STK11 function, correlate with primary resistance to PD-1 axis inhibitors in KRAS-mutant lung adenocarcinoma patients." (PMID 34849607, 2021). "In lung adenocarcinoma, STK11/KEAP1 commutation leads to resistance to pharmacologically induced ferroptosis and high expression of ferroptosis-protective genes, which is associated with early death and aggressive tumor development." (PMID 35047016, 2021). "published a similar study, in which they use CRISPR/Cas9 mediated genome editing to identify LKB1 (STK11) tumor suppressing properties in KRAS-driven lung adenocarcinoma mouse models." (PMID 34781949, 2021). "KRAS mutant lung adenocarcinoma patients with concurrent inactivating mutations in the tumor suppressor genes of KEAP1 and STK11 have demonstrated lower clinical response rates treated with standard chemotherapy or immunotherapies." (PMID 32560187, 2020).
lung adenocarcinoma (continued). "For example, in KRAS-mutant lung adenocarcinoma, STK11/LKB1 mutation is associated with resistance to ICB treatment." (PMID 32110280, 2020). "In a genotypically and phenotypically distinct subset of lung adenocarcinoma cell lines, STK11 inactivation was found to be common and to attenuate the PI3K/AKT pathway." (PMID 32373524, 2020). "This can be explained by the fact that STK11 deletion in KRAS-driven lung adenocarcinoma promotes the accumulation of neutrophils with T-cell suppressive function, as observed in mouse models." (PMID 33114576, 2020). "So, we infer that FGL2 exert synergic effects with STK11 to enhance the cytotoxic T lymphocytes activities in tumor environment of lung adenocarcinoma." (PMID 32206449, 2020). "Serine/threonine kinase 11 (STK11, or liver kinase B1, LKB1) is a tumor suppressor that is often found mutated in lung adenocarcinoma, especially in presence of co-occurring KRAS mutations." (PMID 33114576, 2020). "In LUAC (Lung adenocarcinoma), the carcinogenic KRAS mutation leads to the loss of STK11(LKB1), thereby recruiting neutrophils with T‐cell inhibitory effects, resulting in reduced T‐cell infiltration." (PMID 32875727, 2020). "Remarkably, it was shown that transcription of CPS1 is negatively regulated by liver kinase B1 (also known as serine/threonine kinase 11) in lung adenocarcinoma cell lines." (PMID 31248089, 2019). "Particularly, in patients with KRAS-mutant lung adenocarcinoma, STK11/LKB1 alterations are significantly associated with PD-L1 negativity and promote resistance to PD-1 inhibitors." (PMID 30294272, 2018). "Here, we demonstrate lineage switching of KRAS+ lung adenocarcinomas (ADC) to squamous cell carcinoma (SCC) through deletion of Lkb1 (Stk11) in autochthonous and transplant models." (PMID 28387316, 2017). "Outside these two malignancies, MYC appears strongly connected to STK11 in lung adenocarcinomas, a kinase related with global regulation of cell metabolism among other processes." (PMID 26792175, 2016). "For example, we observed various patterns of gene expression for the STK11 gene, a kinase that plays a pivotal role as a tumor suppressor of lung adenocarcinoma in many cases, that were completely abolished in three cell lines." (PMID 25378332, 2014). "FBN2 disruption precedes the subclonal deletion of genes along chromosome 9p, including significantly mutated known lung adenocarcinoma genes SMARCA4, KEAP1, and STK11." (PMID 25160065, 2014). "Several other driver molecular alterations have been identified in lung adenocarcinoma, including somatic mutations of KRAS, BRAF, STK11, DDR2 and members of the FGFR family, as well as ALK rearrangements." (PMID 24236184, 2013). "Additionally, 18% of lung adenocarcinoma (LUAD) and 5% of lung squamous carcinoma (LUSC) patients have mutations in STK11." (PMID 40647497, 2025). "STK11 loss occurs in approximately 15% of lung adenocarcinomas and is associated with a lack of PD-L1 expression, reduced tumor-infiltrating cytotoxic CD8+ T lymphocytes, and resistance to ICI in patients with KRAS mutant NSCLC." (PMID 41514645, 2025). "Our analysis suggests that designing a MSLN-directed ADC carrying eribulin mesylate as a payload may be beneficial for STK11/KEAP1-mutant lung adenocarcinoma patients." (PMID 39186767, 2024).
lung adenocarcinoma (continued). "Interestingly, our analysis of COX-IS expression in TCGA lung adenocarcinoma cohort demonstrated increased activity of the COX2/PGE2 axis in RAG1 patients, which are associated with STK11/LKB1 co-occurring mutations." (PMID 38635884, 2024). "Lung adenocarcinoma with co-mutations of Kirsten rat sarcoma viral oncogene homologue (KRAS) and loss of function of STK11/LKB1 also reduce tumor T cell infiltration and are predictive of relapse and poor outcome in patients who have undergone anti-PD-1 treatment." (PMID 39766047, 2024). "Patients with STK11/KEAP1-mutant lung adenocarcinoma may experience limited benefit from checkpoint blockade therapies highlighting unmet need for improved treatment strategies." (PMID 39186767, 2024). "In TCGA cohort, STK11 mutation was a significant risk factor for NSCLC in both lung squamous cell carcinoma (LUSC) and lung adenocarcinoma (LUAD) histology in terms of OS [HR=6.81, 95%CI= (2.16, 21.53), P<0.001; HR=1.50, 95%CI= (1.00, 2.26), P=0.051, respectively]." (PMID 38736875, 2024). "Consequently, STK11/LKB1 co-alteration is widely known as an independent predictor of unfavorable outcomes after PD-L1 blockade in lung adenocarcinoma." (PMID 37490263, 2024). "Notably, STK11/LKB1 has been found to be dysregulated in various types of tumors 27, 28, with lung adenocarcinoma exhibiting a higher incidence of mutations." (PMID 37781074, 2023). "STK11/LKB1 mutations have been identified as the unique marker significantly associated with PD-L1 negative lung adenocarcinoma patients." (PMID 37635168, 2023). "STK11/LKB1 tumours are associated with a lower expression of immune markers (e.g., PD-L1) if KEAP1 is co-mutated, correlating to resistance to PD-1 blockade in KRAS-mutated lung adenocarcinoma." (PMID 36980522, 2023). "Tumor heterogeneity across patients is a plausible explanation for this observation: although there are certainly frequently mutated driver genes in lung adenocarcinoma, such as EGFR, KRAS or STK11, only a minority of patients’ tumor is found positive for each of these mutations." (PMID 37938580, 2023). "Interestingly, somatic mutations in NLRP3 together with 10 other genes including KEAP1, KRAS, and STK11 were reported to define a molecular signature associated with a subtype of NSCLC, the lung adenocarcinoma (LUAD)." (PMID 36746533, 2023). "STK11/LKB1 is a distinct subgroup of Kirsten Rat Sarcoma Virus (KRAS)- mutant lung adenocarcinoma." (PMID 35222404, 2022). "Abnormalities in the STK11/LKB1 gene have also been shown to induce lung adenocarcinoma." (PMID 35165542, 2022). "Another study investigated the prognostic value of STK11/KEAP1 mutations in an observational real-world lung adenocarcinoma cohort, and the results suggested that STK11/KEAP1 mutations are prognostic, not predictive biomarkers for immunotherapy." (PMID 35945957, 2022). "Hence, SCD1 is a promising candidate for targeted drug development in STK11/KEAP1 co-mutant lung adenocarcinoma and ameliorated the drug resistance by inducing ferroptosis." (PMID 36439884, 2022).